UGT2B10 (UDP glucuronosyltransferase family 2 member B10)
Description:
UDP-glucuronosyltransferase (UGT) that catalyzes phase II biotransformation reactions in which lipophilic substrates are conjugated with glucuronic acid to increase the metabolite's water solubility, thereby facilitating excretion into either the urine or bile. Specialized in N-glucuronidation of tertiary amine-containing drugs and xenobiotics. Catalyzes N-glucuronidation of tobacco alkaloids, tobacco-specific nitrosamines, tricyclic antidepressants and compounds containing imidazole groups. Major enzyme responsible for detoxification of tobacco-specific nitrosamines. Shows strong preference for tertiary aliphatic and cyclic amines over secondary or primary amines. Does not glucuronidate steroids, hyodeoxycholic acid, or phenolic xenobiotics.
Synonyms: UDPGT2B10
Tractability: Antibody: UniProt predicts a signal peptide or a membrane-spanning region.
Target class: Enzyme; Transferase
Gene: Protein-coding gene on chromosome 4 (68,815,917 to 68,833,559, forward strand). Ensembl gene ENSG00000109181.
Subcellular location: Microsome membrane; Endoplasmic reticulum membrane
Pathways (Reactome):
Drug ADME: Aspirin ADME
Metabolism: Glucuronidation
Gene Ontology:
Molecular function: glucuronosyltransferase activity; UDP-glycosyltransferase activity
Biological process: detoxification; estrogen metabolic process; xenobiotic catabolic process
Cellular component: endoplasmic reticulum membrane
Genetic constraint (gnomAD): Loss-of-function variants: 50 observed, 42.98 expected, observed/expected ratio (o/e) 1.16, 90% interval 0.93 to 1.47. The upper end of that interval is the gene's LOEUF score, 1.47, which puts it in group 6 of 6, group 1 being the genes least tolerant of losing a copy. Missense variants: 682 observed, 610.87 expected, observed/expected ratio (o/e) 1.12, 90% interval 1.05 to 1.19. Synonymous variants: 224 observed, 199.81 expected, observed/expected ratio (o/e) 1.12, 90% interval 1 to 1.25.
Homologues: Orthologues: chimpanzee UGT2B10 (98% identical), zebrafish ugt2a7 (53% identical), zebrafish ugt2b5 (51% identical), zebrafish ugt2b1 (50% identical), zebrafish ugt5a1 (41% identical), zebrafish si:ch73-334d15.1 (41% identical), zebrafish ugt5a2 (41% identical), zebrafish ugt5g1 (39% identical), zebrafish ugt5b4 (39% identical), zebrafish ugt5c1 (38% identical), zebrafish ugt5f1 (38% identical), zebrafish ugt5b2 (38% identical), and 94 more. Paralogues in human: UGT2B11 (91% identical), UGT2B28 (89% identical), UGT2B7 (88% identical), UGT2B4 (86% identical), UGT2B15 (78% identical), UGT2B17 (77% identical), UGT2A2 (59% identical), UGT2A3 (59% identical), UGT2A1 (51% identical), UGT1A1 (44% identical), UGT1A10 (44% identical), UGT1A8 (44% identical), and 9 more.
Diseases named in the same sentence as UGT2B10 in open-access papers:
UGT2B10 is named in the same sentence as 10 diseases in open-access papers, as found by Europe PMC text mining. Sharing a sentence is not in itself a finding about the gene and the disease. The quoted sentences say what the papers report.
melanoma (2 papers, 2012 to 2022). A malignant, usually aggressive tumor composed of atypical, neoplastic melanocytes. "Consistent with the UGT expression pattern observed in melanocytes, the primary melanoma cell line WM115 exhibited only UGT2B7, UGT2B10 and UGT2B15 expression." (PMID 23110092, 2012). "Treatment of WM3211 or metastatic melanoma cell lines with anti-cancer agents (including vemurafenib) induced expression of UGT2B7, UGT2B10 and UGT2B15 demonstrating that melanoma cells retain the ability to re-express these same three UGTs." (PMID 23110092, 2012). "Only a few reports have been published, including research on UGT expression in melanocytes derived from newborn foreskin tissues, with UGT2B isoforms (UGT2B7, UGT2B10, and UGT2B15) being expressed primarily in normal melanocytes as well as in a primary melanoma cell line." (PMID 35682955, 2022). "Interestingly we demonstrate that UGT2B7, UGT2B10 and UGT2B15 can be re-expressed in melanoma cells in response to the anti-cancer agents." (PMID 23110092, 2012).
breast carcinoma (1 paper, 2010). "UGT2B10 and 11 are not yet reported to be associated with MD or breast cancer, but UGT2B10 is involved in the metabolism of tobacco-related nitrosamines." (PMID 20799965, 2010).
lung carcinoma (1 paper, 2021). "Recognizing the contribution of UGT2B10 genotype to serum (or saliva) cotinine levels is critical to understanding the relationship of an individual's cotinine level to smoking exposures and ultimately the relationship to lung cancer risk." (PMID 33932402, 2021).
prostate tumours (1 paper, 2020). "Similar to normal prostate tissue, prostate tumours expressed several UGT2B mRNAs, including UGT2B17 but also UGT2B4, UGT2B7, UGT2B10, UGT2B11, UGT2B15 and UGT2B28." (PMID 32047296, 2020).
UGT2B10 also shares sentences with these, for which no sentence is quoted: cancer (1 paper); dependence (1); metastatic melanoma (1); nicotine dependence (1); prostate carcinoma (1); tumor (1).